EZR (ezrin)
Diseases named in the same sentence as EZR in open-access papers (continued):
Sharing a sentence is not in itself a finding about the gene and the disease.
cancer (continued). "Overexpression of CD44 has been observed in many types of cancer, and the interaction between CD44 and ezrin, radixin, and moesin links the actin cytoskeleton to the plasma membrane and the extracellular matrix." (PMID 32679746, 2020). "Seven target genes, namely DDX5, SOS2, ACTG1, EZR, FN1, HCLS1 and PIK3R5, were involved in proteoglycans in cancer signaling pathway." (PMID 32293320, 2020). "It is well known that ERM complex (Ezrin, Radixin and Moesin) are cytoskeletal molecules connected to CD44 C-terminal domain and are believed to be closely related to cancer malignancy." (PMID 33292278, 2020). "Dermcidin (DCD), ezrin (EZR), and prosaposin (PSAP) are also hyper-secreted in both R273H- and R175H-driven secretome samples and they promote cancer progression." (PMID 32526853, 2020). "We further show that systemic inhibition of ezrin, using a small molecule compound (NSC668394), impedes the migration of cancer cells in vivo." (PMID 30678714, 2019). "Ezrin as a member of the ezrin/radixin/moesin (ERM) protein family plays an important role in regulating the growth and metastatic of cancer." (PMID 31886273, 2019). "Here, we investigated ezrin/NHERF1 interactive effects on spindle dynamics and multicellular assembly in physiological and cancer models." (PMID 29520890, 2018). "Moreover, it has been shown that Ezrin phosphorylation (pY477) could induce the destabilization of adherents junctions and E-cadherin internalization, contributing to cell migration and invasion, suggesting a link between Ezrin and E-cadherin with cancer progression." (PMID 29587669, 2018). "Taken together, these data show that PKCz ameliorates the effects of centrosome amplification via ezrin/NHERF1 interactions, interphase centrosome clustering at the ezrin cap, and suppression of multipolar spindle formation in cancer cells." (PMID 29520890, 2018). "From cancer biology it is known that EGFR and Ezrin form a functional complex, however, their exact interactions are still elusive." (PMID 26881744, 2016). "In this regard, studies on the inhibitory effects of an ezrin inhibitor, NSC668394, on the ezrin-related signaling such as Src and paxillin and on the migration of cancer cells are underway in our researches." (PMID 25866790, 2015). "Hence, it seems that Ezrin might play an important role in the development of cancer." (PMID 26632332, 2015). "Subsequently, Ezrin was knock down by shRNA in ESCC cell line, which led to decrease of the growth, adhesion, and invasiveness of cancer cells in vitro and tumorigenesis in vivo." (PMID 25126570, 2014). "Here, we have studied the intracellular dynamics of PTPD1, a FERM (four-point-one, ezrin, radixin, moesin) domain-containing PTP that is over expressed in cancer cells and potentiates EGFR signalling." (PMID 25062045, 2014). "Ezrin is a member of Ezrin-radixin-moesin (ERM) protein family that plays a key role in cancer progression and metastasis in a wide range of cancers, including CRC." (PMID 24581231, 2014). "Altogether, these data suggest that stimulation of cancer cells to develop invadopodia by plating on ECM, occurs through the formation of a protein-protein complex formed by NHE1, p-ezrin, ß1-integrin, PKA and p-NHERF1." (PMID 24086451, 2013). "We previously showed that overexpression of a truncated amino-terminal domain of ezrin blocks HGF-induced migration and morphogenesis of epithelial cells, and reduces cell scattering in SP1 carcinoma cells expressing activated c-Src." (PMID 15987432, 2005). "Furthermore, combination therapies targeting GPX4 and FAK/Src were found to enhance cancer cell death, and MDM2, ezrin, and cortactin were identified as potential ferroptosis inhibitor targets." (PMID 40164758, 2025). "For example, genes such as VEGFA and EZR were significantly expressed in EC-1-Cancer cells, but genes such as PDE4D and AFDN were not expressed." (PMID 37124501, 2023).
cancer (continued). "Another interesting protein candidate emerging from the ezrin network appeared to be AKT, the component of the PI3K/AKT signaling pathway activated by ezrin in different cancer types and previously demonstrated to mediate de novo vemurafenib resistance in BRAFV600E-expressing RKO cells." (PMID 37629086, 2023). "CD44 is a cancer stem cell marker and is known to interact with OPN, FN1, and Ezrin 36-38." (PMID 34976221, 2022). "Moreover, knocking down of Ezrin and treating with the p38 inhibitor significantly reduced TAM-induced dissemination of cancer cell clusters." (PMID 35680853, 2022). "Finally, we set out to identify L1CAM target genes and investigated the expression of ezrin, galectin‐3, and FGFb, which had already been described as L1CAM targets or binding partners in other cancer entities." (PMID 34228897, 2022). "Altogether, these data suggest that cancer cells develop functional invadopodia and perform subsequent invasion by establishing a compartmentalized, functional “signalsome” inside invadopodia, composed of β1-integrin, ILK, NHE1, p-ezrin and p-NHERF1." (PMID 33671549, 2021). "Ezrin mediates cell growth and survival through Akt signaling, but not the mitogen-activated protein kinase (MAPK) pathway in certain cancers, which is essential for cancer proliferation, invasion, migration and survival." (PMID 33240887, 2020). "Moreover, the finding that in DARTS assays the exposure to Ori or Iru in C2C12 cell line did not cause any detectable protection of Ezrin indicated that this protein could represent a target for the two compounds only in cancer cells: an interesting suggestion to be verified in future work." (PMID 33003361, 2020). "Unlike its role in other cancers, reduced membranous Ezrin expression is related with unfavorable clinicopathological characteristics and an impaired survival." (PMID 33240887, 2020). "In line with this, the inhibition of rho kinase in cultured cells does not prevent ezrin phosphorylation and membrane ruffling (Hep2 cells, a human cancer cell line." (PMID 31382374, 2019). "Additionally, we observed that the expression of cell death regulators such as CYLD, EZR, VAMP1, ANAX1, and FPR1 was increased in mild hyperthermia treated cancer cells, which was similar to LIUS treated cancer cells." (PMID 31355136, 2019). "Of the included 120 cancer samples, 98 cases were positive for ezrin expression and 22 were negative." (PMID 31452341, 2019). "Many studies reported that upregulation of Ezrin is a negative prognostic factor in various cancers." (PMID 31344926, 2019). "Negative effects of ezrin-expression on the prognosis of malignant tumours were also demonstrated in uveal malignant melanoma of the eye." (PMID 31382374, 2019). "To investigate the roles of ERK and ezrin in cancer development, we used the non-woven silica fibre sheet CellbedTM with a structure resembling the loose connective tissue morphology in a novel 3D culture system." (PMID 30344309, 2018). "In this study, we investigated the role of ezrin and ERK in cancer development and determined whether these markers can be used as molecular targets." (PMID 30344309, 2018). "The current results indicate that tumors with high ezrin expression possess adverse biological features already at a stage, when the cancer has not yet disseminated." (PMID 28953975, 2017). "The purpose of this study was to provide a first description of incident UC cases in the Malmö Diet and Cancer Study (MDCS) up until December 31 2010, and to further validate the expression, clinicopathological correlates and prognostic significance of ezrin in UC, not only limited to the bladder." (PMID 25278252, 2014). "Indeed, invasive capacity followed quite closely the pattern of the effect of the ezrin mutants on focal ECM proteolysis, in line with studies suggesting that invadopodia function and p-ezrin are fundamental for cancer cell invasive capacity." (PMID 24086451, 2013).
cancer (continued). "Accumulating evidences showed that ezrin protein expression was markedly increased in a variety of human cancers compared with their non-malignant tissue counterparts." (PMID 24182314, 2013). "The expression of fascin-1 was greater in T1+T2 than T3+T4 cancer (mean rank 119.70 vs. 100.50, P = 0.007), as was that of ezrin (mean rank 102.29 vs. 117.20, P = 0.047) but not paxillin." (PMID 23209815, 2012). "The expression of the 3 proteins was higher with N+ than N0 cancer (P≤0.006) and was higher with stages III+IV than stages I+II cancer (mean rank for fascin-1, 118.95 vs. 97.25, P = 0.002; ezrin 116.68 vs. 99.69, P = 0.022; paxillin: 117.09 vs. 99.25, P = 0.010)." (PMID 23209815, 2012). "The other two significant proteins, PLCG1 and EZR (ezrin), were demonstrated to play critical roles in the metastatic potential of cancer cells but not in primary tumor growth." (PMID 21211025, 2011). "Since effusions are characterized as clusters of detached carcinoma cells, the parallel dysregulation of TSC1 and ezrin expression may play a critical role in effusion formation." (PMID 19680458, 2010). "Cortactin, along with Ezrin, two distinct cytoskeletal organising proteins, are critical in the formation of cellular processes in PDAC, which may aid in invasion and metastasis of cancer cells." (PMID 39849106, 2025). "Thus, elucidating the regulatory mechanisms governing the EZRIN/EGFR axis and its link with mitochondrial metabolism could suggest novel therapeutic strategies, particularly in the context of cancer." (PMID 41145430, 2025). "Even though ezrin has been mostly discussed for its involvement in cancer, it is not known if ezrin could compensate for moesin should the latter be absent or “incapacitated” in mast cells." (PMID 37569454, 2023). "After USP24 knockdown, the levels of P-gp, ABCG2, and ezrin were decreased, which indicated that USP24 as a deubiquitinating enzyme may stabilize P-gp, ABCG2, and ezrin to enhance the ability of pumping out of a drug from cancer cells." (PMID 33846536, 2021). "This prompts the next question whether or not pharmacological regulators with a high affinity to Ezrin would exhibit encouraging results for cancer treatment." (PMID 33240887, 2020). "Of the 120 cancer samples, ezrin expression was positive in 98 cases and negative in 22 cases." (PMID 31452341, 2019). "However, there is an opposite data indicating the involvement of negative or reduced expression of Ezrin in cancer progression." (PMID 31344926, 2019). "Ezrin belongs to the ERM (ezrin-radixin-moesin) protein family and has been demonstrated to regulate early steps of Fas receptor signalling in lymphoid cells, but its contribution to TRAIL-induced cell death regulation in adherent cancer cells remains unknown." (PMID 26010871, 2015). "Ezrin (EZR), the protein with the highest frequency of autoantibodies in both early stage GEM and resectable PDAC patients, was validated by ELISA test using PDAC sera either collected at the time of diagnosis or several months before cancer onset (prediagnostic PDAC)." (PMID 24010981, 2013). "Here, the authors suggest that the variations in malignant phenotypes between LGR5-positive cancer stem cells and LGR5-negative cells could be due to their distinct mechanical phenotypes observed in vitro, determined by the membrane to cortex attachment proteins Ezrin/Radixin/Moesin." (PMID 38637494, 2024). "However, data on the involvement of ezrin in TGCT cancer is absent." (PMID 37373333, 2023). "However, it is not clear whether targeting ezrin would affect already disseminated cancer cells, or their response to chemotherapy." (PMID 36923551, 2022). "Interestingly, as well as merlin, ezrin and willin, we have reported that there appears to be a series of other newly identified FERM containing proteins which can connect the hippo pathway, junctional components and the cytoskeleton all of which can influence cancer." (PMID 27438856, 2016).
cancer (continued). "Furthermore, the stimulation of cancer cells to develop invadopodia by plating on ECM, occurs through the formation of a a lipid raft compartmentalized functional protein-lipid-protein “signalsome” formed by NHE1, p-ezrin, PIP2, ß1-integrin and p-NHERF1 that promotes this activation of NHE1." (PMID 24086451, 2013). "In addition to the increased overall expression of Ezrin in CRC, Ezrin provides a critical scaffold linkage between the plasma membrane and the actin cytoskeleton, thereby enhancing cell motility, invasion, and metastasis in many human cancers, including human CRC cells." (PMID 23755307, 2013).
infection (28 papers, 2009 to 2025). The state of being infected such as from the introduction of a foreign agent such as serum, vaccine, antigenic substance or organism. "Using co-immunoprecipitation assays, we observed a stable association between IL-6R, Lyn and Ezrin in mouse AMs after PAO1 infection." (PMID 29263906, 2016). "Our data point towards a novel role of ezrin as a regulator of early events of infection of susceptible cells by SARS-CoV." (PMID 23185364, 2012). "By comparison of infection by wild type gonococci with a retraction-deficient (pilT-) strain, it has been demonstrated that the formation of cortical plaques containing f-actin, transmembrane proteins, and membrane-cytoskeleton linkers such as ezrin depends on T4P retraction." (PMID 21340023, 2011). "In this context, ezrin recruitment and phosphorylation play an essential role for adhesion and protrusion stabilization 2 h after infection." (PMID 41290585, 2025). "In particular, NSC66 treatment inhibits sustained bacterial adhesion after 2 h of infection, which depends on the β2AR signaling pathway and on ezrin accumulation under colonies." (PMID 41290585, 2025). "After infection, we detected EV markers such as Ezrin, Radixin and Moesin (ERMs), and other EV markers like Milk Fat Globule-EGF Factor 8 (MFG-E8, Lactadherin), but no contamination from other membrane compartments like the endoplasmic reticulum (CALNEXIN)." (PMID 36131943, 2022). "From the example above and the knowledge that a number of viruses require ERMs for their infection process (see Section 3.2), it seems that ezrin is important for many pathogens entry into cells." (PMID 31018575, 2019). "We have reported that an ezrin dominant-negative mutant and siRNA-mediated knockdown of ezrin expression in target cells inhibit infection by the envelope protein (Env) of CXCR4 (X4)-tropic HIV-1." (PMID 30210460, 2018). "We observed that X4-tropic HIV-1 vector infection was inhibited by expression of the EZ-TA mutant but increased by expression of the EZ-TD mutant, suggesting that ezrin phosphorylation in target cells is required for efficient HIV-1 entry." (PMID 30210460, 2018). "Taken together, the down regulation of Ezrin, Radixin and Moesin with ∆potABCD suggest a novel mechanism by which pneumococci can escape host innate immunity and spread infection in the lung by regulating the expression of ERM complex." (PMID 27247105, 2016). "We show that ezrin, by binding to S endodomain, limits S-dependent early events of infection, most likely by affecting efficacy of fusion." (PMID 23185364, 2012). "Localization studies showed that wild-type ezrin was recruited to the filopodia at 15 min post infection; while diffuse cellular staining was observed in cell transfected with the dominant negative ezrin." (PMID 19046338, 2009). "Additionally, infection with these viruses disrupted polarity as demonstrated by re-localization of both ezrin and Na/K ATPase." (PMID 35452499, 2022). "However, JEV enters human brain microvascular endothelial cells via an endocytic pathway mediated by caveolae and the ezrin protein and also targets dopamine-rich areas for infection of the midbrain via altering dopamine levels." (PMID 36560690, 2022). "For example the infection of HIV-1 via CXCR4 co-receptor requires phosphorylated ezrin." (PMID 31018575, 2019). "As one of the reasons, unphosphorylated ezrin may bind to a cellular factor that is required for infection by released viral particles." (PMID 30210460, 2018). "Infection of SW480 cells with a retroviral vector encoding these constructs led to variable but appreciable expression levels of ezrin mutants, with the exception of the nonphosphorylatable variant Y145F, that was mostly expressed in the insoluble fraction." (PMID 26010871, 2015). "Expression of the ezrin dominant negative FERM domain enhanced cell susceptibility to infection by SARS-CoV and S-pseudotyped particles and potentiated S-dependent membrane fusion." (PMID 23185364, 2012).